TRIM59 (tripartite motif containing 59)
Diseases named in the same sentence as TRIM59 in open-access papers (continued):
Sharing a sentence is not in itself a finding about the gene and the disease.
steatosis (2 papers, 2023). Increased lipid within the cytoplasm of cells. "Overexpression of TRIM59 can promote the steatosis of L02 cells, and the application of DFO can significantly reverse this effect." (PMID 37867509, 2023). "In L02 cells, PA notably increased the level of steatosis whereas overexpressed TRIM59 further promoted the steatosis." (PMID 36417114, 2023). "The application of ferroptosis inhibitor defetoxamine (DFO) can significantly improve TRIM59-mediated steatosis and inflammation." (PMID 37867509, 2023). "The application of DFO, the ferroptosis inhibitor, significantly attenuated TRIM59-induced steatosis and inflammation in NAFLD." (PMID 36417114, 2023). "In L02 cells, PA treatment notably intensified steatosis levels, elevated TRIM59 expression, and enhanced the secretion of tumor necrosis factor alpha (TNF-α), interleukin 6 (IL-6), and interleukin 8 (IL-8)." (PMID 37867509, 2023). "TRIM59 promotes steatosis and ferroptosis in MAFLD by enhancing GPX4 ubiquitination, and inhibition of TRIM59 can effectively improve the process of MAFLD." (PMID 37867509, 2023). "Amplifying the expression of TRIM59 further exacerbated steatosis and substantially heightened the secretion of TNF-α, IL-6 and IL-8." (PMID 37867509, 2023). "Meanwhile, the level of steatosis was promoted by HFD but decreased by the inhibition of TRIM59." (PMID 36417114, 2023). "In summary, our study revealed that TRIM59 could promote steatosis and ferroptosis in NAFLD via enhancing GPX4 ubiquitination." (PMID 36417114, 2023). "The inhibition of TRIM59 could inhibit the steatosis and inflammation in NAFLD, whereas its overexpression exhibited reversed effects." (PMID 36417114, 2023). "The application of ferroptosis inhibitor, DFO, could markedly ameliorate steatosis and inflammation, which was mediated by overexpressed TRIM59." (PMID 36417114, 2023). "The application of ferroptosis inhibitor, deferoxamine, could markedly ameliorate steatosis and inflammation, which was mediated by overexpressed TRIM59." (PMID 36417114, 2023). "The inhibition of TRIM59 could inhibit the steatosis and inflammation in NAFLD cell model, whereas its overexpression exhibited reversed effects." (PMID 36417114, 2023). "ORO staining revealed that the application of PA notably promoted the level of steatosis, whereas the knockdown of TRIM59 could reverse this effect." (PMID 36417114, 2023). "Results indicated that the elevated expression of TRIM59 could promote steatosis in L02 cells, whereas the application of DFO could notably reverse this effect." (PMID 36417114, 2023). "In our study, we found that TRIM59 could promote the steatosis and inflammation in NAFLD cell model, and the inhibition of TRIM59 was a promising strategy to ameliorate NAFLD both in vitro and in vivo." (PMID 36417114, 2023). "GPX4 expression was decreased in liver tissues of mice fed with HFD; the knockdown of TRIM59 could elevate GPX4 expression and decrease steatosis." (PMID 36417114, 2023). "In conclusion, TRIM59 can promote MAFLD steatosis and ferroptosis by enhancing GPX4 ubiquitination, and inhibiting TRIM59 can effectively improve the MAFLD process, so TRIM59 may be a potential target for MAFLD treatment." (PMID 37867509, 2023).
adenoma (1 paper, 2015). A neoplasm arising from the epithelium. "Such analyses identified three genes (ACVR2A, TGFBR2, and SLC22A9) and an additional two genes (TCERG1 and TRIM59) whose mutations were enriched for clonal and adenoma-specific categories, respectively." (PMID 26336987, 2015).
atherosclerosis (1 paper, 2022). A disease characterized by the build-up of fatty material and calcium deposition in the arterial wall resulting in partial or complete occlusion of the arterial lumen. "TRIM59 has been confirmed to be highly expressed in the liver of mice, and it may be a potential therapeutic target for inflammatory diseases such as atherosclerosis." (PMID 36360326, 2022).
Autoimmunity (1 paper, 2018). The occurrence of an immune reaction against the organism's own cells or tissues. "This seems to further support the hypothesis of the involvement of TRIM59 in cellular senescence since chronic neuro-inflammation has been shown to be important in aging and neuro-degeneration, while autoimmunity is known to induce inflammation, tissue damage and remodelling." (PMID 29466246, 2018).
breast invasive carcinoma (1 paper, 2018). "Particularly, in breast invasive carcinoma (BRCA), TRIM59 mRNA level was significantly increased in tumor sites (red plot) compared with its expression in normal adjacent tissues (blue plot; fold change = 4.03, P value = 2.9 × 10−28)." (PMID 30408026, 2018).
breast tumor (1 paper, 2018). "Among the 87 matched samples, we detected markedly higher intensities of TRIM59 immunostaining in breast tumors than in tumor-adjacent normal tissues." (PMID 30408026, 2018). "To understand the molecular mechanisms by which TRIM59 promotes breast tumor growth, we performed quantitative functional proteomics studies on MCF7 cells (TRIM59 KD or KO versus control) by using a high-throughput reverse phase protein array (RPPA)." (PMID 30408026, 2018). "Given our observations that TRIM59 was up-regulated in human breast tumors and that TRIM59 stabilizes PDCD10 protein, we asked whether PDCD10 is essential for breast tumor growth and if the expression of PDCD10 is correlated with TRIM59." (PMID 30408026, 2018).
cerebral cavernous malformation (1 paper, 2018). A disorder characterized by malformations in the structure of the capillaries in the brain. "We show that TRIM59 regulates the degradation of PDCD10, which is involved in programmed cell death and is the main factor for driving the pathogenesis of the devastating familial cerebral cavernous malformation (CCM) disease." (PMID 30408026, 2018).
endometrial cancer (1 paper, 2021). Primary or metastatic malignant neoplasm involving the endometrium (mucous membrane that lines the endometrial cavity). "A previous study used Immunohistochemistry (IHC) to determine the expression of TRIM59 in 291 cases of 37 tumor types, and found that TRIM59 expression was upregulated in tumor samples, particularly in lung, breast, liver, skin, tongue and mouth (squamous cell cancer) and endometrial cancers." (PMID 34534244, 2021).
familial Alzheimer disease (1 paper, 2020). A degenerative disease of the brain that causes gradual loss of memory, judgment, and the ability to function socially. "Moreover, TRIM59 and KLF14 hypermethylation in blood cells may be a valuable predictor of the molecular processes underlying familial Alzheimer’s disease." (PMID 32020847, 2020).
HIV-1 infection (1 paper, 2015). The type species of lentivirus and the etiologic agent of acquired immunodeficiency syndrome (AIDS). "While the TRIM family of proteins is important in innate immune responses, we find TRIM59 to be downregulated in HIV-1 infection." (PMID 26426037, 2015).
pulmonary diseases (1 paper, 2023). "TRIM59 participates in the development of pulmonary diseases." (PMID 37978515, 2023).
renal carcinoma (1 paper, 2025). A carcinoma arising from the epithelium of the renal parenchyma or the renal pelvis. "Abnormal lipid metabolism significantly contributes to renal cancer progression; however, the relationship between TRIM59 and lipid metabolism has not been reported." (PMID 40790033, 2025).
renal cell carcinoma (1 paper, 2019). "TRIM59 also serves as a pro-oncogenic protein in promoting the progression of renal cell carcinoma (RCC)." (PMID 31137886, 2019).
sarcoma (1 paper, 2018). A usually aggressive malignant neoplasm of the soft tissue or bone.
Stroke (1 paper, 2024). Sudden impairment of blood flow to a part of the brain due to occlusion or rupture of an artery to the brain. "In the current work, bioinformatic analysis was carried out to screen genes in stroke related to ubiquitination, and TRIM59 was shown to be expressed at low levels in cerebral I/R animal and cell models." (PMID 38291200, 2024). "Bioinformatic analysis indicated that tripartite motif-containing protein 59 (TRIM59) is downregulated in stroke, which was verified in cerebral I/R models." (PMID 38291200, 2024).
triple-negative breast carcinoma (1 paper, 2019). An invasive breast carcinoma which is negative for expression of estrogen receptor (ER), progesterone receptor (PR), and human epidermal growth factor receptor 2 (HER2). "Importantly, the level of TRIM59 overexpression in triple negative breast carcinoma (TNBC) is higher than that in non-triple negative breast carcinoma." (PMID 30974870, 2019).
tumor (48 papers, 2017 to 2026). "This exposes the nuclear localization sequence of TRIM59 and facilitates its nuclear localization, wherein TRIM59 subsequently degrades macroH2A1, a tumor-suppressive histone variant, and inhibits TC45 from the dephosphorylation of STAT3." (PMID 38727267, 2024). "PDCD10 overexpression can accelerate tumor migration, invasion through reversing TRIM59 loss-induced contractile phenotypes." (PMID 34733794, 2021). "Nuclear TRIM59 then promotes the tumor-suppressive histone variant macroH2A1 ubiquitination and degradation, leading to enhanced STAT3 signaling activation and tumorigenicity." (PMID 31488827, 2019). "PDCD10 overexpression or administration of a ROCK inhibitor reversed TRIM59 loss-induced contractile phenotypes, thereby accelerating cell migration, invasion, and tumor formation." (PMID 30408026, 2018). "TRIM59 deficiency suppressed primary tumor growth at early stages (around 8 weeks postinjection)." (PMID 30408026, 2018). "It is likely that the rs1141023 polymorphism may mediate higher expression level of TRIM59 protein and therefore play a role in the etiology of cancers with advanced tumor infiltration." (PMID 28009992, 2017). "We identified TRIM59 as an independent poor prognostic factor, with its high expression correlating with an immunosuppressive tumor microenvironment (TME)." (PMID 42245669, 2026). "For instance, tumor-derived exosomes transfer tripartite motif-containing 59 (TRIM59) to macrophages, inducing the ubiquitination of abhydrolase domain-containing 5 (ABHD5), activating pro-tumor functions in macrophages." (PMID 38655063, 2024). "TRIM59, a constituent of the TRIM protein family, has been implicated in the initiation and advancement of diverse tumor types." (PMID 38062041, 2023). "Eugenol’s tumour-suppressive activity was totally eliminated by ectopic TRIM59 expression, highlighting TRIM59′s predominate function in modulating the signalling that follows eugenol therapy." (PMID 36770859, 2023). "Some genes (TRIM22/TRIM38/TRIM5/TRIM59) are expressed lower in tumor cells than in other cell types." (PMID 35928444, 2022). "The limitation of this study lies in the fact that it is only the data analysis of biological database, and further verification of TRIM59 expression level and follow-up information are needed in clinical samples for each specific tumor type." (PMID 34534244, 2021). "Detection of TRIM59 expression in these tumor tissues is helpful for us to evaluate the prognosis of patients." (PMID 34534244, 2021). "In this study, the cancer genome atlas (TCGA) and gene expression omnibus (GEO) datasets were used to analyze the expression of TRIM59 in tumors and evaluate the value of TRIM59 as a biomarker for tumor diagnosis and prognosis." (PMID 34534244, 2021). "In subsequent studies, it was shown that upregulation of TRIM59 can promote tumor growth in tumor cell lines and animal models, while downregulation had the opposite effect." (PMID 34534244, 2021). "Receiver operating characteristic curve (ROC) results provided further evidence for the use of TRIM59 as a potential tumor diagnosis biomarker." (PMID 34534244, 2021). "We analyzed 15 types of tumor datasets that included sufficient numbers of tumors and adjacent normal tissues in TCGA, confirming that TRIM59 was highly expressed in tumor samples in comparison to their adjacent tissues." (PMID 34534244, 2021). "It has been found that down-regulation of TRIM59 significantly inhibited tumor growth in vitro experiments and animal models." (PMID 34534244, 2021). "Our findings also indicate that tumor-derived exosomal TRIM59 has an important role in intercellular communication for fostering an inflammatory microenvironment and promoting lung metastasis." (PMID 32867817, 2020). "Similar to TRIM24, an increased expression of TRIM59 has been demonstrated in CRC samples and is associated with advanced tumor stage of CRC patients." (PMID 33066016, 2020).
tumor (continued). "In this study, we demonstrated that interaction between LC cells and macrophages by exosomal TRIM59 results in dysregulated NLRP3 inflammasome activity that drive macrophages-mediated tumor progression." (PMID 32867817, 2020). "Our findings also indicated that tumor-derived exosomal TRIM59 has an important role in intercellular communication for fostering an inflammatory microenvironment and promoting lung metastasis." (PMID 32867817, 2020). "By contrast, overexpression of TRIM59 increased the volume and weight of the xenograft tumours and promoted tumour growth in vivo." (PMID 30515965, 2019). "The present study provides experimental evidence that TRIM59 is overexpressed significantly in LC and the immunostaining intensity of TRIM59 positively correlates with a more aggressive tumour phenotype." (PMID 30515965, 2019). "A forest plot revealed that high expression levels of TRIM59 correlate with poor OS in tumor patients (HR = 1.43, 95%CI: 1.24–1.66, P < .001)." (PMID 31770215, 2019). "As far as we know, this is the first meta-analysis to investigate the prognostic role of TRIM59 in tumor patients." (PMID 31770215, 2019). "We look forward to future studies and original data concerning the relationship between TRIM59 and tumor biology." (PMID 31770215, 2019). "In our study, we found that deletion of TRIM59 further enhanced the tumor-promoting actions of M2 macrophages by inducing production and the release of TNF-α." (PMID 31600735, 2019). "This study demonstrates that CDK5 promotes GBM tumor growth through TRIM59-mediated STAT3 signaling activation." (PMID 31488827, 2019). "TRIM59 knockdown (KD) promoted apoptosis and inhibited tumor growth, while TRIM59 overexpression led to the opposite effects." (PMID 30408026, 2018). "We next performed in vivo imaging analysis to monitor the effect of TRIM59 on tumor metastasis in NSG mice injected with MCF7-luc or MDA-MB-231-luc cells (luciferase-expressing stable cells)." (PMID 30408026, 2018). "The tumor weight and volume were substantially reduced in mice bearing TRIM59 KD MCF7 cells when compared with control mice." (PMID 30408026, 2018). "Targeting TRIM59—through small molecule inhibitors, RNA interference, or emerging approaches such as PROTACs—could potentially restore apoptosis sensitivity in tumor cells." (PMID 40790033, 2025). "Therefore, IRF6 overexpression reversed the ability of TRIM59 to promote glycolysis-dependent tumor cell growth." (PMID 40796729, 2025). "TRIM59 participates in tumour disease progression by regulating the ubiquitination of genes." (PMID 38291200, 2024). "Moreover, the results of RT-qPCR, western blotting, and IHC assays performed on PC specimens and adjacent non-tumor samples revealed an increase in TRIM59 expression in PC tissues." (PMID 39725730, 2024). "Additionally, in the MC38 transplanted tumor model, the knockout of TRIM59 resulted in increased activation of M1 macrophages." (PMID 38992114, 2024). "Furthermore, based on the OncoVar online database, TRIM16, TRIM59, TRIM62, and TRIM71 genes were shown to act as tumor mutation drivers." (PMID 35873464, 2022). "TRIM59 is a protein that is highly expressed in a variety of tumors and promotes tumor development." (PMID 34534244, 2021). "To explore the value of high expression of TRIM59 in tumors, we tested if TRIM59 could be used to identify healthy and tumor samples." (PMID 34534244, 2021). "However, no large-scale clinical studies have been performed to demonstrate the relationship between TRIM59 and tumor diagnosis and prognosis." (PMID 34534244, 2021). "Additionally, TRIM59 have a high efficacy in diagnosis and prognosis prediction in various tumor types." (PMID 34534244, 2021).